PRSS41 (serine protease 41)
Synonyms: TESSP1
Gene: Protein-coding gene on chromosome 16 (2,798,470 to 2,805,304, forward strand). Ensembl gene ENSG00000215148.
Subcellular location: Cell membrane
Pathways (Reactome):
Metabolism of proteins: Post-translational modification: synthesis of GPI-anchored proteins
Genetic constraint (gnomAD): Loss-of-function variants: 37 observed, 25.22 expected, observed/expected ratio (o/e) 1.47, 90% interval 1.12 to 1.87. The synonymous counts are far from expectation, so gnomAD's model fits this gene poorly and the ratio says little. Missense variants: 431 observed, 376.07 expected, observed/expected ratio (o/e) 1.15, 90% interval 1.06 to 1.24. Synonymous variants: 195 observed, 153.03 expected, observed/expected ratio (o/e) 1.27, 90% interval 1.13 to 1.43.
Homologues: Orthologues: mouse Prss41 (58% identical), rat Prss41 (55% identical), tropical clawed frog prss29 (35% identical), Drosophila melanogaster Sb (27% identical), Drosophila melanogaster CG17242 (17% identical). Paralogues in human: PRSS21 (53% identical), TMPRSS9 (33% identical), HPN (33% identical), TMPRSS11F (33% identical), TMPRSS11D (32% identical), TMPRSS3 (32% identical), TMPRSS6 (32% identical), ST14 (32% identical), TMPRSS15 (32% identical), TMPRSS5 (32% identical), TMPRSS13 (31% identical), TMPRSS7 (31% identical), and 5 more.
Diseases named in the same sentence as PRSS41 in open-access papers:
PRSS41 is named in the same sentence as 2 diseases in open-access papers, as found by Europe PMC text mining. Sharing a sentence is not in itself a finding about the gene and the disease. The quoted sentences say what the papers report.
colorectal cancer (1 paper, 2023). A primary or metastatic malignant neoplasm that affects the colon or rectum. "On the contrary, the testis-specific serine proteases, such as PRSS56 and PRSS41, were greatly reactivated in stomach cancer and colorectal cancer." (PMID 37400936, 2023).
PRSS41 also shares sentences with these, for which no sentence is quoted: stomach cancer (1 paper).